PHLDA1 (pleckstrin homology like domain family A member 1)
Diseases named in the same sentence as PHLDA1 in open-access papers (continued):
Sharing a sentence is not in itself a finding about the gene and the disease.
neuroblastoma (continued). "Our transcriptomic and proteomic analyses aimed at elucidation of the role of PHLDA1 in neuroblastoma, as its role in different cancers remains not yet fully elucidated." (PMID 38495105, 2024). "This suggests that patients with MYCN-amplification might benefit the most from anti-GD2 treatment which significantly activates PHLDA1 expression, at least in IMR-32 neuroblastoma cell line." (PMID 38495105, 2024). "To investigate how the ch14.18/CHO-treatment affects PHLDA1 protein interactors in neuroblastoma cells, we compared potential PHLDA1 binding proteins in control- and the antibody-treated IMR-32 cells by co-immunoprecipitation, using anti-PHLDA1 antibodies followed by mass spectrometry." (PMID 38495105, 2024). "Importantly, our results indicate that PHLDA1 silencing enhances the EGF receptor signaling pathway and combinatory treatment of gefitinib and ch14.18/CHO antibodies might be beneficial for neuroblastoma patients." (PMID 38495105, 2024). "Taken together, our data imply that PHLDA1 silencing enhances the EGF receptor signaling pathway, but the influence is unidirectional since neither EGFR activation, nor inhibition does not generate changes in the PHLDA1 level in shCtrl cells and IMR-32 neuroblastoma cells." (PMID 38495105, 2024).
trichoblastoma (7 papers, 2017 to 2025). A benign hair follicle neoplasm with trichoblastic differentiation. "Immunohistochemical staining showed that nearly all desmoplastic trichoepitheliomas tested were PHLDA1-positive." (PMID 39630301, 2025). "PHLDA1 was also identified as a follicular stem cell marker in desmoplastic trichoepitheliomas, benign skin lesions originating from the hair follicle." (PMID 39630301, 2025). "Pleckstrin homology like domain family A member 1 is a hair follicle bulge marker positive in trichoblastomas, trichoepitheliomas, and desmoplastic trichoepitheliomas." (PMID 39282518, 2024). "Similarly, the increased PHLDA1 expression was reported by other groups in trichoblastoma, a tumor originating from germinative cells of the hair follicle." (PMID 39630301, 2025). "In the recent years, the antibody direct against PHLDA-1, a marker of follicular epithelial stem cells, has been proposed as the most reliable marker for the differential diagnosis with “mimickers”, mostly trichoblastoma (TBL)/trichoepithelioma (TEP) and basaloid follicular hamartoma (BFH)." (PMID 32759706, 2020).
gastric cancer (6 papers, 2018 to 2025). A primary or metastatic malignant neoplasm involving the stomach. "The relationship between circ_0027599 and miR-101 levels in gastric cancer tissues indicated that circ_0027599 expression was positively associated with PHLDA1 expression." (PMID 30410722, 2018). "We also analyzed the relationship between circ_0027599 and PHLDA1 levels in gastric cancer tissues, and the data indicated that circ_0027599 expression was positively associated with PHLDA1 expression." (PMID 30410722, 2018). "Yet another group showed that PHLDA1 mRNA is a target of miR-101 in gastric cancer, as shown by using bioinformatic analysis and luciferase reporter assay." (PMID 39630301, 2025). "The results showed that the circ_0027599 decreased the proliferation and metastasis of gastric cancer cells via miR-101/PHLDA1." (PMID 30410722, 2018). "CCK8 assay showed that circ_0027599 decreased the colony numbers in the gastric cancer cells with miR-101 overexpression or down-regulating PHLDA1 expression." (PMID 30410722, 2018). "In the present work, we observed that PHLDA1 expression was significantly down-regulated in gastric cancer cells and tissues." (PMID 30410722, 2018). "The miR-101 mimics can significantly decrease protein expression level of PHLDA1 in the gastric cancer cells." (PMID 30410722, 2018). "The data indicated that circ_0027599 decreased the invasion or migration ability of the gastric cancer cells with PHLDA1 siRNA or miR-101 transfection." (PMID 30410722, 2018). "The results indicated that circ_0027599 was effectively up-regulated in the gastric cancer cells, PHLDA1 protein was up-regulated and miR-101 was down-regulated." (PMID 30410722, 2018). "The study uncovered that PHLDA1 was regulated by circ_0027599/miR-101, which suppressed gastric cancer survival and metastasis in gastric cancer." (PMID 30410722, 2018). "We used RT-PCR to verify the most potential target genes and found that PHLDA1 mRNA was significantly down-regulated in gastric cancer cells with miR-101." (PMID 30410722, 2018). "The study was aimed to investigate the role of circRNAs in regulating PHLDA1 expression in gastric cancer." (PMID 30410722, 2018). "In this study we attempted to characterize the molecular mechanisms of the suppressing role of PHLDA1 in gastric cancer." (PMID 30410722, 2018). "In our present study, functional analysis revealed that miR-101 stimulated cell growth, migration, and invasion, indicating that miR-101 could function as an onco-miRNA in gastric cancer by targeting PHLDA1." (PMID 30410722, 2018). "It was also verified that PHLDA1 was regulated by circ_0027599 in gastric cancer cells." (PMID 30410722, 2018). "PHLDA1 is a nuclear protein that has been postulated as a biomarker in the early detection and/or therapy of gastric cancer, but never before has been associated with asthma disease." (PMID 29977241, 2018). "In gastric cancer, PHLDA1 is down-regulated and may be a tumor inhibitor." (PMID 30410722, 2018). "Transwell system was used to observe the gastric cancer cell invasion ability and the result showed that the invaded cells became less in MKN-28 and HGC-27 cells with PHLDA1 overexpression." (PMID 30410722, 2018). "We demonstrated that PHLDA1 suppressed the migratory and invasive abilities of MKN-28 and HGC-27 gastric cancer cells." (PMID 30410722, 2018). "Pleckstrin homology-like domain family A member 1 (PHLDA1) is a tumor suppressor gene in gastric cancer, but its role regulated by circular RNAs (circRNAs) is not known." (PMID 30410722, 2018).
Obesity (6 papers, 2013 to 2025). Accumulation of substantial excess body fat. "Additionally, we investigated five genes, PRDM2, CXCL1, PHLDA1, DIDO1, CDA, which were commonly expressed in all datasets including depression, obesity, diabetes, and NASH." (PMID 34833079, 2021).
osteosarcoma (6 papers, 2015 to 2025). A usually aggressive malignant bone-forming mesenchymal neoplasm, predominantly affecting adolescents and young adults. "The inhibition of miR-526b-5p enhanced the level of PHLDA1 and was associated with osteosarcoma progression." (PMID 39630301, 2025). "Additionally, in mice xenograft models, lower PHLDA1 expression slows the progression of overall survival metastasis, while high PHLDA1 expression is linked to high tumor progression in osteosarcoma cells." (PMID 38921000, 2024). "Plus, we detected the expression IHC staining results of PHLDA1 in osteosarcoma tissues and the paired adjacent tissues: PHLDA1 was more in osteosarcoma tissues than in adjacent tissues." (PMID 32983961, 2020). "Collectively, circ0085539 functionally promoted osteosarcoma progression by sponging miR-526b-5p to release PHLDA1." (PMID 32983961, 2020). "Our research not only provided evidence that PHLDA1 was osteosarcoma promotive but also enriched the downstream network of miR-526b-5p in osteosarcoma." (PMID 32983961, 2020). "On the other hand, a downstream signaling of PHLDA1 in osteosarcoma remains unstudied in this research, which is also worth further exploring." (PMID 32983961, 2020). "Functionally, circ0085539 significantly promoted the progression of osteosarcoma through sponging miR-526b-5p to release PHLDA1." (PMID 32983961, 2020). "The study identified PHLDA1 mRNA as a target of miR-526b-5p in osteosarcoma cells." (PMID 39630301, 2025). "Lastly, whether PHLDA1 promotes metastasis of osteosarcoma remains to be further studied, as osteosarcoma is a highly metastatic malignancy." (PMID 32983961, 2020). "PHLDA1 might be a downstream target of miR-526b-5p that significantly upregulated in human osteosarcoma." (PMID 32983961, 2020). "Meanwhile, the tumor inhibition in response to PHLDA1 knockdown could be restored by miR-526b-5p inhibition, strongly suggesting PHLDA1 as a downstream target of miR-526b-5p to promote osteosarcoma tumorigenesis." (PMID 32983961, 2020). "In our research, we identified PHLDA1 as a potential downstream effector of miR-526b-5p and found that the apoptotic suppression capacity of PHLDA1 showed enormous advantages over its apoptotic activation capacity in osteosarcoma cells." (PMID 32983961, 2020). "Circ0085539–miR-526b-5p–PHLDA1 axis could act as a novel target for therapy of osteosarcoma." (PMID 32983961, 2020). "However, PHLDA1 silencing did not affect the viability or proliferation rate of MG63.3 osteosarcoma cells." (PMID 39630301, 2025). "Mechanistically, the authors showed that PHLDA1 silencing resulted in the downregulation of the activities of MAPKs, i.e., ERK1/2, c-Jun N-terminal kinases (JNK), and p38 mitogen-activated protein kinase in MG63.3 osteosarcoma cells, as shown by kinase array assay." (PMID 39630301, 2025).
ovarian carcinoma (6 papers, 2021 to 2025). A malignant neoplasm originating from the surface ovarian epithelium. "Only three out of ten MPAS genes (PHLDA1, EPHA2, and DUSP4) displayed reproducible associations with baseline levels and changes in MEK/ERK activity across most ovarian cancer model systems and clinical samples." (PMID 36362153, 2022). "Levels of PHLDA1, DUSP4, and EPHA2 expression were also significantly associated with baseline levels of MEK/ERK pathway activity in multiple human ovarian cancer cell lines and ovarian cancer patient samples available from the TCGA database." (PMID 36362153, 2022). "We evaluated possible associations between the expression of PHLDA1, SPRY4, EPHA2, and DUSP4 and MEK/ERK pathway activity in 20 ovarian cancer cell lines." (PMID 36362153, 2022). "Here, we examined the expression of PHLDA1 in human ovarian cancer (OvCa), the most lethal gynecologic malignancy, and investigated its functions in vitro." (PMID 34405011, 2021). "For instance, overexpression of ankyrin repeat domain 1 (ANKRD1) or pleckstrin homology like domain family A member 1 (PHLDA1) in ovarian carcinoma correlates with poor survival, and upregulation of these proteins in OC cell lines modulates cell apoptosis via the ERS pathway." (PMID 37817482, 2023). "PHLDA1 protein inhibits Akt and has tumor‐suppressive ability in breast and ovarian cancers." (PMID 36289533, 2022). "Only 3 of 10 MPAS genes (PHLDA1, DUSP4, and EPHA2) reflect MEK/ERK pathway activity significantly and consistently across multiple experimental models and clinical tissue samples of ovarian cancer." (PMID 36362153, 2022). "Among the PHLDA family, PHLDA1 might serve as a therapeutic target for several cancers, such as colon, ovarian, and pancreatic cancer, while PHLDA2 might be used as a therapeutic target for esophageal, kidney, and ovarian cancer." (PMID 38921000, 2024).
hepatocellular carcinoma (5 papers, 2020 to 2025). A malignant tumor that arises from hepatocytes. "This LINC01093/miR-155-3p/PHLDA1 regulatory axis led to decreased cell proliferation and induced apoptosis of hepatoma cells, therefore adding to the group of results demonstrating decreased potential of tumor progression." (PMID 39630301, 2025). "Yet another example of sponging miRNA, and the last described here in relation to PHLDA1, was found in hepatoma." (PMID 39630301, 2025). "The second study on hepatoma revealed that PHLDA1 mRNA is also a direct target of miR-3682-3p." (PMID 39630301, 2025). "The decreased expression of miR-3682-3p was associated with increased PHLDA1 levels in hepatoma cells, pointing once again to the negative correlation between PHLDA1 and miRNAs." (PMID 39630301, 2025). "PHLDA1 was downregulated and could act as a protective prognosis biomarker in hepatocellular carcinoma." (PMID 34434692, 2021).
atherosclerosis (4 papers, 2013 to 2023). A disease characterized by the build-up of fatty material and calcium deposition in the arterial wall resulting in partial or complete occlusion of the arterial lumen. "Inflammatory macrophage cluster identified from an atherosclerosis mouse model showed high-level expression of various genes previously assigned to a pro-atherogenic role (e.g., Ccl3, Il1b, Il1a, Nlrp3, Cebpb, Egr1, and Phlda1)." (PMID 38149246, 2023).
endometrial cancer (4 papers, 2018 to 2025). Primary or metastatic malignant neoplasm involving the endometrium (mucous membrane that lines the endometrial cavity). "PHLDA1 was found to be substantially associated with disease-free survival in patients with thyroid cancer, head and neck squamous cell carcinoma, pancreatic cancer, soft tissue sarcoma, bladder cancer, and endometrial cancer, as well as with overall survival in these patients." (PMID 40688078, 2025). "A significant decrease in H3K4me3 and H3K27ac at the PHLDA1 locus was also observed in MFE-296 endometrial cancer cells treated for seven days with the FGFR inhibitor PD173074." (PMID 37047202, 2023). "Similar to endometrial cancer cells, knockdown of PHLDA1 alone, by 48-hr treatment with small interfering RNA (siRNA), was sufficient to generate de novo resistance to trastuzumab." (PMID 29490281, 2018). "The most striking result from our microarray analysis was that, in both populations of resistant endometrial cancer cell lines, the Pleckstrin Homology-Like Domain-containing protein, PHLDA1, was the most strongly downregulated gene." (PMID 29490281, 2018). "Using fibroblast growth factor receptor (FGFR) inhibition in endometrial cancer cells, we identify an Akt-driven compensatory mechanism underpinned by downregulation of PHLDA1." (PMID 29490281, 2018). "Interestingly, in a microarray profiling for transcriptional target of FGFR inhibitor (FGFRi) in endometrial cancer cells, PHLDA1 was identified as the most significantly downregulated gene in the resistant cells." (PMID 37225844, 2023). "Since the development of RTKi resistance in our endometrial cancer model was dependent on a resurgence in Akt activity, we examined whether the re-sensitization of resistant cells following PHLDA1 induction was mediated by a suppression of Akt signaling." (PMID 29490281, 2018). "Having determined that PHLDA1 downregulation can underpin tyrosine kinase inhibitor resistance in endometrial cancer cell lines, we investigated whether this was a more global phenomenon in resistance to RTK-targeted therapy." (PMID 29490281, 2018). "The treatment of FGFR2-driven MFE-296 endometrial cancer cells with the FGFR inhibitor PD173074 was also shown to decrease H3K4me3 and H3K27ac at the PHLDA1 locus, and levels of PHLDA1 in this model were also found to be regulated by a PKC/MAPK-mediated pathway." (PMID 37047202, 2023).
Hepatic steatosis (4 papers, 2013 to 2025). Steatosis is a term used to denote lipid accumulation within hepatocytes. "Subsequent in vivo experiments established that depletion of Phlda1 in mice liver could induce the hepatic steatosis, which suggested that Phlda1 might be a key indicator of steatosis." (PMID 35038982, 2022).
Insulin resistance (4 papers, 2017 to 2025). Increased resistance towards insulin, that is, diminished effectiveness of insulin in reducing blood glucose levels. "Interestingly, PHLDA1 is induced by IGF-1 and insulin upregulates IGF-1 receptors in conditions with insulin resistance, as in PCOS." (PMID 28068351, 2017).
liver cancer (4 papers, 2020 to 2025). An epithelial or non-epithelial malignant neoplasm that arises from the liver. "In short, PHLDA1 plays a role of inhibitor in liver cancer, which inhibited cell division and accelerate apoptosis." (PMID 33033502, 2020).
pancreatic cancer (4 papers, 2014 to 2025). "Following the previous analysis, immunofluorescence was performed on the tumor sample and adjuvant tumor sample, and the findings indicated that PHLDA1 was expressed primarily in CAFs in pancreatic cancer." (PMID 40688078, 2025). "Together, our findings suggest that PHLDA1 serves as a prognostic biomarker in pancreatic cancer and influences tumor growth by modulating cancer-cell proliferation and migration." (PMID 40688078, 2025). "In four pancreatic cancer datasets, including the TCGA-GTEX cohort, PHLDA1 expression was remarkably elevated in the pancreatic cancer samples." (PMID 40688078, 2025). "We considered each of the four tumor categories for PHLDA1 based on the level of expression: glioblastoma, colon, kidney, and pancreatic cancers." (PMID 38921000, 2024). "Overall, our assessments of patient survival performed on a variety of platforms, such as R2, Oncomine, and PrognoScan, highlighted the oncogenic significance of PHLDA1 in brain and pancreatic cancer." (PMID 38921000, 2024). "Here, it was found that PHLDA1 is highly correlated with genes found in brain, colon, kidney, and pancreatic cancers." (PMID 38921000, 2024). "Based on mRNA expression and clinical data from Oncomine and TCGA, we infer that PHLDA1 has an oncogenic role in the case of brain, colon, lymphoma, kidney, and pancreatic cancers." (PMID 38921000, 2024). "In summary, a comprehensive analysis of survival data from a range of online resources highlighted the oncogenic role of PHLDA1 in brain cancer and pancreatic cancer." (PMID 38921000, 2024). "According to survival analysis, patients with high PHLDA1 expression had a worse prognosis than patients with low PHLDA1 expression, which suggested that PHLDA1 could be a possible prognostic marker for pancreatic cancer." (PMID 40688078, 2025). "Also, the expression of PHLDA1 in clinical samples of patients with pancreatic cancer was subsequently described." (PMID 40688078, 2025). "This hypothesis underpins our investigation into the prognostic and functional significance of PHLDA1+ CAFs in pancreatic cancer." (PMID 40688078, 2025). "Through the examination of seven key genes’ expression levels, only PHLDA1 was highly expressed in CAFs in the pancreatic cancer group, suggesting that this gene could be a potential procancer CAF marker." (PMID 40688078, 2025). "Next, we investigated the role of PHLDA1 in the development of pancreatic cancer." (PMID 40688078, 2025). "Therefore, targeting PHLDA1 might not only disrupt the detrimental crosstalk between CAFs and tumor cells but also enhance the efficacy of conventional therapies, offering a promising new avenue for pancreatic cancer treatment." (PMID 40688078, 2025). "Translating this platform to PHLDA1^high CAF-rich pancreatic tumors could normalize the microenvironment, attenuate CAF-mediated immunosuppression, and potentiate the efficacy of PHLDA1-targeted therapies and immune checkpoint blockade." (PMID 40688078, 2025). "This suggests that targeting PHLDA1+ mCAFs, either alone or in combination with interventions aimed at other CAF subtypes, could provide a more comprehensive strategy for disrupting tumor–stroma interactions and improving therapeutic outcomes in pancreatic cancer." (PMID 40688078, 2025).
steatosis (4 papers, 2019 to 2024). Increased lipid within the cytoplasm of cells. "NAMPT, PHLDA1, RALGDS, GADD45B, and FOSL2 were all in the brown module, with a lower expression for steatosis and NASH samples and with a higher expression for normal samples." (PMID 34041361, 2021). "Fatty liver is known to occur in both under- and overnutrition; our results suggest that this might reflect regulatory disruptions in a core set of genes, including NDUFS2 and PHLDA1, that lead to steatosis regardless of the directional effect of the nutritional insult." (PMID 31857576, 2019).